MYC (MYC proto-oncogene, bHLH transcription factor)
Diseases named in the same sentence as MYC in open-access papers (continued):
Sharing a sentence is not in itself a finding about the gene and the disease.
prostate carcinoma (continued). "The degradation of MYC partners by PROTACs has proven successful in clinical models for ARV-771, which depletes the expression of MYC by degrading of BET proteins even in castration-resistant prostate cancer and MZ1, which exhibited anticancer effects in acute myeloid leukemia by targeting MYC." (PMID 38896334, 2024). "Accordingly, a recent study unveiled a novel metabolic function of MYC in regulation of fatty acid synthesis in prostate cancer, indicate that inhibition of fatty acid synthesis by targeting MYC ACLY/ACC1/FASN axis may be a viable strategy for prevention and/or therapy of prostate cancer." (PMID 39538125, 2024). "MYC is downstream of AR and promotes prostate cancer cell growth even in the absence of androgens." (PMID 35935969, 2022). "Infection of cultured DU145 prostate cancer cells with adenovirus expressing MXI1 resulted in decreased cell proliferation and a higher proportion of cells in the G /M phase of the cell cycle, and decreased c-MYC expression by MXI1 resulted in cell growth arrest." (PMID 35602303, 2022). "Notably, downregulation of MYC is not a general feature of prostate cancer growth arrest, as the highly active chemotherapy agent docetaxel did induce growth arrest of LNCaP cells but did not cause downregulation of MYC." (PMID 36194476, 2022). "Dose-dependent effects were monitored in PC-3 prostate cancer cells, as well as in previously identified PPRH-sensitive AsPc-1 pancreatic cancer cells, where strong dose- and time-dependent effects on cell viability and growth and MYC transcription and translation were observed." (PMID 36613820, 2022). "Additionally, in prostate cancer cells, the synthetic androgen mibolerone inhibited proliferation and reduced levels of c-MYC transcripts, suggesting that AR is important for regulating c-MYC levels." (PMID 33062889, 2020). "Collectively, our data demonstrate that elevated MYC in a subset of primary prostate cancers functions in a negative role in regulating MEIS1 expression, and that this down-regulation may contribute to MYC-driven development and progression." (PMID 32681068, 2020). "Interestingly, in MYC-driven lung adenocarcinoma, OCT1 binding sites were enriched in a set of genes regulated by MYC, suggesting that OCT1 and MYC may also co-regulate a subset of androgen responsive genes in prostate cancer." (PMID 33134178, 2020). "However, targeted disruption of BRD4 function also results in tumor cell killing in a variety of solid tumors where MYC does not appear to be a major cancer driver, including certain lung cancers, prostate cancers, and glioblastoma." (PMID 32796829, 2020). "Our results defined significant genomic alterations in MYC pro-oncogene networking, as well as TGF-β signaling—including androgen/TGF-β signaling inhibitor PMEPA1 responding to curcumin treatment in both androgen-dependent and independent prostate cancer cells." (PMID 31581661, 2019). "For example, the expression levels of cancer-drivers/oncogenes MYC, MYB, and AR, whose roles in prostate cancer have been well established, were consistently lower in both TSPX-overexpressing LNCaP cells and TSPX-high clinical prostate cancer samples than the corresponding controls." (PMID 30863497, 2019). "Indeed, dietary fat intake does not only amplify the MYC transcriptional program in MYC-driven prostate cancers, but can enrich for it, even in cancers lacking MYC over expression." (PMID 31554818, 2019). "The intriguing observation that altered ERG expression can significantly affect C-MYC levels in the VCaP cells prompted us to re-examine Type I/Type II ratios and C- MYC expression from our previously published qRT-PCR data from laser capture micro- dissected (LCM) prostate cancer cells." (PMID 25221645, 2014).
prostate carcinoma (continued). "Suppression of c-Myc and its downstream targets was most pronounced in cells lines exhibiting the greatest sensitivity to I-BET762, suggesting that perturbations in MYC pathways may contribute to the growth effects observed in prostate cancer cell lines." (PMID 24293458, 2013). "In a separate study, we found that MYC regulates a number of genes and gene sets related to ribosome biogenesis and nucleolar function in human prostate cancer cells, and that fibrillarin, which is one of 51 MCS genes, is necessary for prostate cancer cell proliferation." (PMID 22039435, 2011). "Thus, MYC plays a role in various types of cancer, not just prostate cancer." (PMID 39595075, 2024). "Interestingly, HNRNPF expression showed a positive correlation with MYC hallmarks and thus was not consistent with the observed effects of hnRNP F. Loss of hnRNP H/F altered cell cycle progression and induced apoptosis in the PC3 prostate cancer cell line." (PMID 37399401, 2023). "Altogether, our findings suggest that a substantial subset of prostate cancer patients, including some without MYC amplification, may benefit from epigenetic therapies targeting MYC transcriptional activity or from dietary interventions targeting the metabolic dependencies regulated by MYC." (PMID 31554818, 2019). "This hypothesis could explain the results of Wang and colleagues showing that Pim1 depletion by RNA interference in mouse and human prostate cancer cells decreased cellular proliferation, survival, Erk signaling and tumorigenicity even when MYC levels were not significantly altered." (PMID 23565217, 2013). "We also included MYC/PVT1-neutral cell lines (no amplification and no translocation): U2OS (osteosarcoma), BxPC-3 (pancreatic ductal adenocarcinoma) and DU145 (prostate cancer) as controls." (PMID 40027648, 2025). "On the other hand, the expression levels of MYC and MYB in TSPX-low prostate cancer samples were significantly higher than those in both non-tumor prostate samples and TSPX-high prostate cancer samples." (PMID 30863497, 2019). "Strikingly none of the NEPC tumors with TNC amplification was independent of the alterations of the master genes ERG and MYC, indicating a selective co-segregation of TNC along with MYC and ERG amplification in the subtype of aggressive prostate cancers." (PMID 31798767, 2019). "In three prostate cancer cell lines (LNCaP, VCaP, and PC3), pharmacologically inhibition of OGT decreased MYC protein stability without affecting its mRNA levels." (PMID 23964270, 2013). "Although the ESRP1 gene is located on chromosome 8 close to the MYC oncogene (an important oncogene that is also frequently amplified in prostate cancer), ESRP1 amplification can be observed in prostate tumours independently of MYC alterations, indicating that it is not a bystander event." (PMID 37752235, 2023). "Our results did not rule out the possibility that prostate cancer subtypes with alteration in ERG and MYC may exist in NEPC, without an involvement of TNC through alternative pathways." (PMID 31798767, 2019). "In a recent study in prostate cancer cells, it was shown that PCAT1 attenuates the downregulation of MYC protein expression (but not mRNA amount or stability) by interfering with miR-34a, a known miRNA that regulates MYC expression by targeting the MYC mRNA 3′UTR." (PMID 27077133, 2015). "This phenomenon has also been shown in human prostate cancer, in which PIM1 is most likely to collaborate with MYC in cellular transformation as it is the most consistently expressed gene among MYC-positive and MYC-negative prostate cancer tumor samples." (PMID 23565217, 2013). "To further query the how suppressing elevated MYC in cancer cells may affect circadian gene expression, we leveraged publicly available data where PC3 prostate cancer cells, known to have high endogenous (non-amplified) MYC levels, were treated with the new generation MYC inhibitor MYCi361." (PMID 37639465, 2023).
prostate carcinoma (continued). "It is common for a NE prostate cancer phenotype to not express AR and PSA and common for amplification of the genes aurora kinase A (AURKA) and N-myc (MYCN, both of which were overexpressed in ACRJ-PC28 at RNA-seq level and MYC was detected at the protein level." (PMID 36643868, 2022).
colorectal cancer (623 papers, 1998 to 2026). A primary or metastatic malignant neoplasm that affects the colon or rectum. "Live-cell time-lapse imaging of the colorectal cancer cells COLO320DM with ecDNA encoding the MYC oncogene (ecMYC) indeed showed synchronous segregation of ecDNA and chromosomal DNA during cell division." (PMID 41278658, 2025). "In colorectal cancer, one of the most frequently activated downstream molecules is MYC, a gene associated with cell proliferation." (PMID 40525649, 2025). "In colorectal cancer, MYC mutations occur in adenomas, and drastic changes in downstream metabolic enzymes and the metabolism have been observed." (PMID 36769322, 2023). "Colorectal cancer (CRC) frequently has a dysregulated epigenome causing aberrant up-regulation of oncogenes such as c-MYC." (PMID 36313707, 2022). "ACYP expression is associated with the metastatic phenotype of human colorectal cancer and plays an oncogenic role in gliomas via activating the c-MYC signaling pathway." (PMID 35586489, 2022). "MYC is overexpressed and involved in colitis-associated colorectal cancer; PCNA is also upregulated in colorectal cancer." (PMID 34595169, 2021). "Yu Y. and colleagues demonstrated that FoxO3a, a transcriptional factor with an important regulatory function in the CRC cell survival, confers cetuximab resistance in RAS mutated colorectal cancer cell lines through a c-MYC induced expression." (PMID 32164324, 2020). "Colorectal cancer risk and c-MYC rs6983267 association was derived from an analysis of 923 patients and 1846 controls." (PMID 33007997, 2020). "Our results describe a role for the MYC-regulated SNHG15 locus in colorectal cancer, role dependent on the lncRNA encoded by this bifunctional gene." (PMID 31014355, 2019). "Another article reported that a TCF7L2 missense variant rs138649767 associates with colorectal cancer risk by interacting with a GWAS-identified regulatory variant rs698326 in the MYC enhancer." (PMID 30627228, 2018). "Adding to the involvement of risk alleles on MYC, our analysis also highlighted rs6983267, which has been shown in colorectal cancer to interact with MYC and rs4242382, affecting the expression of MYC and POU5F1B." (PMID 29560112, 2018). "A mutated form of c-MYC is found in many human cancers, including lung cancer, breast cancer, cervical cancer, ovarian cancer, and in colon and colorectal cancer, where Myc is constitutively expressed." (PMID 27218803, 2016). "MYC, located on chromosome 8q24 in humans, harbors multiple, upstream risk loci for human prostate, bladder, breast, and colorectal cancer." (PMID 25955013, 2015). "In particular, overexpression of c-MYC has been found in various cancer cells 2 including colorectal cancer cells 3,4 and is often associated with poor prognosis." (PMID 25689483, 2015). "MYC hypomethylation was previously associated with the oncogenic progression and metastasis induction in a rat model of liver cancer and in human colorectal cancer samples." (PMID 23717612, 2013). "Together, these results point to an impact on Wnt signaling and MYC expression as a strong candidate for the biological mechanisms connecting the rs6983267 variant to risk of colorectal cancer." (PMID 21129217, 2010). "Overexpression of c-MYC also constitutes an early event after loss of the APC tumor suppressor gene that initiates colorectal cancer." (PMID 18190704, 2008). "Furthermore, we found enhanced c-MYC rescued colorectal cancer cell progression caused by UBQLN1 silencing." (PMID 37370699, 2023).
colorectal cancer (continued). "Our previous study found that MYC is closely associated with BMI1 in colorectal cancer." (PMID 36208024, 2023). "Importantly, the MYC-mediated downregulation of miR-29a-3p has been described in colorectal cancer and associated with an increased migration of tumor cells." (PMID 36499093, 2022). "Indeed, a study that investigated the effects of the deletion of a MYC enhancer that is implicated in colorectal cancer showed that the deletion led to cancer resistance while having only slight or no impact on MYC expression." (PMID 27282637, 2016). "Moreover, depletion of PVT1 by small interference RNAs (siRNAs) caused the reduction of MYC protein levels in a human colorectal cancer cell line and nuclear colocalization of PVT1 and MYC was also shown." (PMID 25883951, 2015). "Moreover, enhanced c-MYC rescued colorectal cancer cell progression caused by UBQLN1 silencing." (PMID 37370699, 2023). "By combining small-molecule disruption of the MYC-MAX protein-protein interaction with pharmacological activation of the 20S proteasome, we induce rapid and pronounced depletion of MYC in MYC-dependent colorectal cancer cell lines." (PMID 42319868, 2026). "Results obtained with a preclinical TNIK inhibitor in human colorectal cancer cells show efficient abrogation of MYC expression and consequently impaired dimerization with its interaction partner MAX." (PMID 41785318, 2026). "Previous colorectal cancer studies conform with our findings, and it has been demonstrated that MYC regulates tumor proliferation through various mechanisms, including CLK3 and the Wnt/β-catenin pathway." (PMID 41201451, 2026). "Here we map the 3D architecture of MYC-amplified ecDNA in colorectal cancer cells and identify 68 ecDNA-interacting elements—genomic loci enriched for transposable elements that are frequently integrated onto ecDNA." (PMID 41120733, 2025). "ChIP-qPCR analysis confirmed c-MYC as a transcriptional regulator of PTBP1 in colorectal cancer cells." (PMID 40469179, 2025). "ACP-1n inhibits BRD4 function in the nucleus of colorectal cancer cells by blocking LLPS to suppress SE-driven MYC expression." (PMID 40231263, 2025). "Here, it is found that squamocin effectively depletes both EZH2 and MYC in multiple cancer cell lines, including head and neck squamous cell carcinoma, and gastric and colorectal cancer, demonstrating potent efficacy in suppressing these in vivo tumor models." (PMID 39823459, 2025). "We discovered that SLC35A2 enhances MYC expression in CRC, and since MYC is a crucial transcription factor promoting colorectal cancer progression 2, this suggests a potential role for SLC35A2 in cancer development." (PMID 40303483, 2025). "It has been shown that overexpression of the MYC gene in colorectal cancer promotes the malignant development of tumors." (PMID 39852139, 2025). "We also validated the decrease of TCF1, MYC, and β‐catenin in the reverted colorectal cancer cells by western blot analysis." (PMID 39661721, 2025). "In colorectal cancer cells, mutations in the APC gene activate the Wnt/β‐catenin pathway, resulting in increased c‐MYC transcription." (PMID 40525649, 2025). "The lncRNA CCAT1-L, for instance, interacts with the CTCF protein to modulate chromatin looping at the MYC locus, influencing MYC expression in colorectal cancer cells." (PMID 40282307, 2025). "Functional assays in multiple colorectal cancer cell lines with varying MYC copy numbers demonstrated a time-dependent increase in cell death following sponge transfection." (PMID 40940795, 2025).